LUC7L (LUC7 like)
Description:
May bind to RNA via its Arg/Ser-rich domain.
Synonyms: LUC7B1; hLuc7B1; Luc7; SR+89
Tractability: PROTAC: ubiquitination databases record sites on it; its protein half-life has been measured.
Gene: Protein-coding gene on chromosome 16 (188,961 to 229,463, reverse strand). Ensembl gene ENSG00000007392.
Subcellular location (Human Protein Atlas): Nucleoplasm; Mitochondria
Gene Ontology:
Molecular function: identical protein binding; protein binding; mRNA binding; RS domain binding
Biological process: mRNA splice site recognition
Cellular component: U1 snRNP; U2-type prespliceosome
Genetic constraint (gnomAD): Loss-of-function variants: 27 observed, 45.36 expected, observed/expected ratio (o/e) 0.6, 90% interval 0.44 to 0.82. The upper end of that interval is the gene's LOEUF score, 0.82, which puts it in group 3 of 6, group 1 being the genes least tolerant of losing a copy. Missense variants: 385 observed, 489.92 expected, observed/expected ratio (o/e) 0.79, 90% interval 0.72 to 0.86. Synonymous variants: 173 observed, 176.44 expected, observed/expected ratio (o/e) 0.98, 90% interval 0.87 to 1.11.
Homologues: Orthologues: macaque LUC7L (100% identical), chimpanzee LUC7L (97% identical), mouse Luc7l (97% identical), rat Luc7l (95% identical), dog LUC7L (94% identical), pig LUC7L (82% identical), tropical clawed frog luc7l (79% identical), zebrafish luc7l (78% identical), rabbit LUC7L (61% identical), Drosophila melanogaster CG7564 (55% identical), Caenorhabditis elegans luc-7L (30% identical). Paralogues in human: LUC7L2 (75% identical), LUC7L3 (38% identical).
Diseases named in the same sentence as LUC7L in open-access papers:
LUC7L is named in the same sentence as 4 diseases in open-access papers, as found by Europe PMC text mining. Sharing a sentence is not in itself a finding about the gene and the disease. The quoted sentences say what the papers report.
α-thalassemia (6 papers, 2012 to 2023). "Specifically, in α-thalassaemia the genomic deletion in the 3′-end of forward LUC7L gene produces an elongated transcript that overlaps the HBA2 reverse gene." (PMID 34215320, 2021). "One study of a patient with inherited α-thalassemia identified a deletion of the LUC7L 3' end that allowed aberrant transcription of LUC7L through the downstream HBA2 gene, causing its silencing and the disease phenotype." (PMID 23721193, 2013). "For example, the hemoglobin α1 gene (HBA1) in α-thalassemia patients is repressed by antisense transcription, where an aberrant LUC7L (putative RNA-binding protein Luc7-like) RNA runs antisense to the HBA1 locus and methylates the CpG island at the promoter to repress the HBA1 gene expression." (PMID 30669611, 2019). "In α-thalassemia, the deletion locus of the LUC7-like (LUC7L) gene is co-located with Hemoglobin α 2 (HBA2), an α globin gene, resulting in methylation of the HBA2 promoter." (PMID 22735547, 2012).
breast carcinoma (1 paper, 2020). "LUC7L is rarely studied and encodes a putative RNA-binding protein, contributing to the metastasis of breast cancer." (PMID 33287830, 2020).
LUC7L also shares sentences with these, for which no sentence is quoted: cancer (1 paper); microcytic anemia (1).